AFP (alpha fetoprotein)
Diseases named in the same sentence as AFP in open-access papers (continued):
Sharing a sentence is not in itself a finding about the gene and the disease.
tumor (continued). "Since the AFP value correlates with grade, progression, and survival, our algorithm seems to work independently from the pathological characteristics of the tumours." (PMID 32752173, 2020). "In 2016 they introduced barcodes for the multiplexed detection of five different tumour biomarkers in serum (AFP, CEA, CA199, CA125, and CA242)." (PMID 33276535, 2020). "For example, a nomogram consisting of 7 clinical factors, including age, AFP, PT, magnitude of hepatectomy, postoperative complication, number of tumor nodules, and microvascular invasion, was developed and validated using the data of 617 HCC patients." (PMID 33520012, 2020). "It was also noted that rapid tumor growth, AFP levels, and gain of chromosome 20 were all indicators for chemotherapy resistance and poorer prognosis." (PMID 31979130, 2020). "Remarkably, AFP levels were lower or undetectable in the vehicle groups of TC1 and TC4 compared to the AFP levels at start of treatment, even though tumour volume increased." (PMID 33144587, 2020). "Independent factors included in the nomogram were ECOG performance status, AFP level ≥ 400 μg/L, tumor size ≥ 10 cm, portal vein tumor thrombosis, and IVCTT classification." (PMID 32322268, 2020). "Previous studies have reported associations of tumor size or the presence of PVT, but even HCCs with low serum AFP can exhibit large size, suggesting other factors must be associated with serum AFP level in HCC." (PMID 33371894, 2020). "The poor performance of total AFP in detecting very early HCC has led to a past interest in identifying tumor markers." (PMID 32492896, 2020). "Only the AFP level (p = 0.009), number of tumors (p = 0.012), maximum diameter of the largest tumor (p = 0.015), and tumor grade (p = 0.045) were related to HCC recurrence." (PMID 32635931, 2020). "Serum AFP as a marker of tumour burden has been previously proposed as a prognostic marker in patients undergoing TACE for uHCC." (PMID 32471447, 2020). "Multivariate analysis showed that serum AFP level >150 ng/mL and PET standardised uptake value (SUV) ratio (tumour/background liver) >1.15 were significant risk factors for both RFS and OS." (PMID 33053849, 2020). "In multivariate regression analysis, AFP, TB, and maximum tumor size were found to be independent predictors of poor OS in LDR patients (p=0.008, 0.043, 0.045)." (PMID 33425729, 2020). "Biological roles of AFP during embryonic development and tumor growth have long been investigated; however, they are still not fully understood." (PMID 32019136, 2020). "AFP is one of the most widely used tumor markers for the diagnosis of HCC, and it has a sensitivity of 60% at a cutoff value of 20 ng/mL." (PMID 32382558, 2020). "In present study, we found that overexpression of the CD13 protein was significantly correlated with elevated AFP, tumor encapsulation, microvascular invasion, and high CNLC stage." (PMID 33377659, 2020). "The significance of serum AFP levels has also been shown in treatment using sorafenib, since the tumor control rate is higher in patients with low serum AFP levels than in those with high serum AFP levels." (PMID 32275701, 2020). "Tumor tissue expression of proteins AFP, TGFBR2, pSMAD2, E-cadherin, PIVKAII, cMET and Glypican-3 was analysed to determine relationship to clinical outcomes in Part A or Part B, separately or combined." (PMID 32210440, 2020). "Lower alpha-fetoprotein (AFP) values and early tumor shrinkage contributed to better progression-free survival (PFS)." (PMID 33105621, 2020). "The stepwise multivariable regression identified albumin, Ln(bilirubin), macrovascular invasion, extrahepatic spread, largest tumour size and Ln(AFP) as statistically significant prognostic factors." (PMID 31579990, 2020). "Of note, the data of tumor size and metastasis status were missed in two AFP-positive HCC patients, so these two patients were excluded from the tumor metastasis analysis." (PMID 33014866, 2020).
tumor (continued). "We opted to use human AFP (hAFP) as a model antigen, which is one of the best-characterized tumor markers for HCC27." (PMID 33128033, 2020). "This trial will estimate the maximum tolerated dose, the safety, and ORR of the combination of sorafenib and nivolumab, along with the DOR, PFS, OS, peripheral and tumor immune cell profiling, PD-L1 expression, and alpha-fetoprotein (AFP) response." (PMID 33585218, 2020). "In univariate analysis, serum AFP level, status of ascites, tumor size, tumor number, macrovascular invasion, microvascular invasion and NCSTN expression were identified as potential variables correlated to OS or RFS of HCC patients." (PMID 32631394, 2020). "Cox regression analyses revealed that a tumour number equal to or greater than two (HR 1.54), AFP > 400 μg/l (HR 1.14), serum albumin < 3.6 g/dl (HR 1.63) and total bilirubin > 0.9 mg/dl (HR 1.58) were independent risk factors in our population." (PMID 32125515, 2020). "Several tumor markers, including AFP, AFP-L3 and DCP, have been established specifically for disease management in patients with HCC3,5,31,32." (PMID 32221384, 2020). "Clinical characteristics of HCC patients involving age, gender, BMI, family history of cancer, histologic grade, clinical stage, topography (T), lymph node (N), metastasis (M), residual tumor, tumor status, vascular invasion, Child-Pugh, AFP, new tumor event." (PMID 33115417, 2020). "Among these parameters, AFP, tumor size, the BCLC stage and serum miR-223-3p were selected for multivariate analysis." (PMID 32330203, 2020). "Results of routine blood and urine examination as well as tumor markers including AFP, AFP-L3, CEA, CA199, CA125 and SCC were within the normal range." (PMID 33176766, 2020). "IQGAP1 expression was positively correlated with the expressions of HBsAg and AFP, tumour size and number, and BCLC stage." (PMID 32632148, 2020). "It is well known that patients with high AFP producing tumors have worse tumor biology and have worse outcomes." (PMID 32582866, 2020). "We assessed the weighted parameters for tumor recurrence in the MoRAL-AI with the deep learning method: tumor diameter, followed by alpha-fetoprotein, age, and PIVKA-II." (PMID 33003306, 2020). "The effect of isoform-specific HIFα ASO treatment on HCC tumorigenesis was further investigated via assessment of hepatic mRNA expression of the HCC tumor markers α-fetoprotein (AFP) and glypican-3 (GPC3)." (PMID 33400730, 2020). "In the current study, we identified seven unfavorable prognostic factors for OS in patients with SLHCC after curative resection: tumor size, microvascular invasion, tumor differentiation, Ki67 (%), AFP, CA125, and HBsAg status." (PMID 33312945, 2020). "Albumin level ≥35 g/L, AFP <100 μg/L, PIVKA-II level <100 mAU/mL, and maximum tumor size <5 cm were associated with a significantly improved prognosis in univariate analysis (p<0.05)." (PMID 33112547, 2020). "The group with an AFP model score >2 had a higher proportion of patients with micro-vascular invasion and macro-vascular invasion and with pathological stages of tumor." (PMID 32974380, 2020). "Tumoural markers (alpha-fetoprotein, beta-human gonadotropin chorionic) and hormone levels (testosterone) contribute to the diagnosis and management of a testicular mass in boys." (PMID 32462465, 2020). "The interaction between AFP and retinoic acid receptor (RAR) disrupts the entry of RAR into the nucleus and alters the expression of some tumor-associated genes, such as Fn14 and GADD15326,27." (PMID 33009373, 2020). "According to the univariate factor analysis, older age, worse pathological grade, larger tumor size, lymph node metastases, lower AFP level, and late TNM and SEER stages were significantly related to a worse prognosis (p < 0.05)." (PMID 32110489, 2020).
tumor (continued). "Stage I disease is characterized as tumor confined to the testicle with normal post-orchiectomy tumor markers alpha-fetoprotein (AFP), beta-human chorionic gonadotropin (HCG), lactate dehydrogenase (LDH), and absent metastases on CT scan." (PMID 33585206, 2020). "Immunohistochemical staining of these tumor cells revealed immunoreactivity with AFP and Glypican-3." (PMID 31898539, 2020). "Univariate analysis indicated that ATAD2 expression status, tumor size, metastasis, serum AFP, and TNM stage unfavorably influenced OS." (PMID 32462022, 2020). "Kaplan–Meier analysis showed that AFP, Edmondson grade, tumour size, envelope, tumour number, vascular invasion, GSN expression, and tumour-node-metastasis (TNM) stage were risk factors for DFS and OS." (PMID 32377190, 2020). "Tumor formation was associated with upregulated mRNA expression of the established HCC tumor markers AFP and GPC3." (PMID 33400730, 2020). "TACE with sorafenib plus ICI treatment was a protective predictive factor for PFS, while BCLC stage, AFP level, and tumor size were poor predictive factors for PFS." (PMID 33521054, 2020). "AFP has been shown to inhibit estrogen receptor (ER)-positive tumor growth, which can be attributed to its estrogen-binding ability." (PMID 32019136, 2020). "Changes in AFP ratio of AFP secreting (>20 ng/ml) patients were estimated in different categories of tumor response." (PMID 33614488, 2020). "The ITH signature was also correlated with early tumor recurrence in the Heptromic Cohort, as well as with higher levels of the poor prognostic biomarker alpha-fetoprotein." (PMID 31941899, 2020). "In agreement, variables related to tumor aggressiveness (AFP > 100, multinodular HCC) were independently and strongly associated with shorter time-to-IDR (median time-to-IDR ≈ 6 months) in our series." (PMID 32013112, 2020). "The results indicate that many mutated genes were associated with distinct clinical factors, including BCLC stage, gender, age, AFP, vascular invasion, and tumor size." (PMID 32017470, 2020). "It has been shown that in patients with mVI, factors like tumor size, number, and AFP level play a decisive role in eventual recurrence-free outcomes." (PMID 33553240, 2020). "Abundant studies have concluded the main causes for high HCC recurrence after surgery, including microvascular invasion, poor tumor grade, larger tumor diameter, ischemia time, vascular invasion and elevated AFP 5-7." (PMID 32226523, 2020). "One study reported that independent predictors of MVI included tumor diameter > 2 cm, alpha-fetoprotein (AFP) > 200 ng/mL and PIVKA-II > 40 mAU/mL." (PMID 33129301, 2020). "Compared to AFP, tumor diameter, and preoperative CTC count, the multiparameter combination was the most significant predictor of MVI and helped to guide the options for surgical methods." (PMID 33129301, 2020). "Nonetheless, in the Post‐TACE‐Predict model, response was clearly an independent prognostic factor, in addition to tumor number, tumor size, AFP, bilirubin, and VI." (PMID 31698504, 2020). "In a large series on 655 patients, Lee and his colleges found that AFP/TTV >1.5 was an independent risk factor for HCC recurrence especially if associated with TTV ≥40 cm3, macrovascular invasion, or main tumor diameter ≥ 4 cm." (PMID 32426129, 2020). "Based on the clinicopathological information, we found that a higher level of IQGAP1 expression was positively correlated with HBsAg and AFP level, tumour size and number and BCLC stage." (PMID 32632148, 2020). "In this study we analysed the prognostic factors associated with overall survival in patients undergoing repeat TACE and in particular the impact of the tumour marker alpha-fetoprotein (AFP)." (PMID 32471447, 2020). "The median AFP level was 76,131 (range, 10–1,881,360) ng/ml and the median tumour diameter was 10.6 (range, 5.1–15.8) cm." (PMID 32386507, 2020).
tumor (continued). "In this study, 95 patients were involved, and age, sex, hepatitis B positive rate, tumor size, alpha-fetoprotein (AFP) positive rate, abnormal prothrombin positive rate, and Child-Pugh grade were all proved to be homogeneous." (PMID 32508913, 2020). "The high levels of ATAD2 protein were correlated with tumor size (P = 0.018), metastasis (P = 0.009), serum alpha-fetoprotein (AFP) (P = 0.010), and TNM stage (P = 0.033)." (PMID 32462022, 2020). "Through the Cox proportional hazards regression analysis, we selected seven independent predictors, age, race, AJCC stage, degree of tumour differentiation, tumour size, AFP and tumour therapy, and included them in the prognostic scoring model." (PMID 32117619, 2020). "A total of 216 patients with complete information, including gender, age, clinical stage, tumor grade, T stage, platelet content, albumin content, alpha‐fetoprotein (AFP) content, as well as vascular invasion, were enrolled into the TCGA HCC cohort." (PMID 32813933, 2020). "Among the 233 patients included in TCGA-LIHC cohort with complete clinical information, a higher risk score was found to be significantly correlated with female sex, advanced tumor grade, vascular invasion and higher AFP." (PMID 32514252, 2020). "Consistently, our results also indicated that E2F8 was up-regulated in HCC tumors and correlated with advanced tumor stage and AFP elevation." (PMID 31990034, 2020). "In terms of risk factors for EDR and LDR, we found that tumor size and HBV-DNA were associated with EDR, while AFP, TB, and tumor size were related to LDR." (PMID 33425729, 2020). "In multivariate analysis, alpha fetoprotein (AFP) > 100 ng/mL (OR = 3.027; p = 0.037) and tumor size (OR = 1.06; p = 0.001) were independently associated with IDR (internal validation by bootstrapping)." (PMID 32013112, 2020). "Multivariate analysis was performed using the Cox Proportional hazards model and the analysis revealed that GSTA1, AFP, tumor number, PVTT and TNM were independent prognostic factors for HCC (all P < 0.05)." (PMID 31892975, 2020). "Whereas, alanine and aspartate aminotransferase levels, albumin, HBV DNA level, PLR, AFP, tumor encapsulation, microvascular invasion, multiple HCC, tumor differentiation, and tumor size were associated with worse OS." (PMID 33178607, 2020). "Serum levels of the tumor makers alpha-fetoprotein (AFP) and protein induced by vitamin K antagonists-II (PIVKA-II) were elevated to 81,663 ng/ml (normal < 10 ng/ml) and 238 mAU/ml (normal < 40 mAU/ml), respectively." (PMID 32430849, 2020). "At present we have selected an AFP TCR with the optimal affinity, function, and safety profile, bearing properties that are expected to allow AFP TCR redirected T cells to specifically differentiate between AFP levels on tumor and normal tissues." (PMID 32425926, 2020). "Univariate Cox analysis also indicated that there was significant correlation between tumor size, serum AFP levels, microscopic vascular invasion, Edmondson-Steiner grade, SPATS2 up-regulation and overall survival (p < 0.05)." (PMID 33411682, 2020). "NUDT1 mRNA expression positively correlates with the level of AFP expression (P = 0.000), pathological tumor stage (P = 0.038), tumor size (P=0.031), tumor grade (P = 0.000), and the degree of vascular invasion (P = 0.005)." (PMID 32341205, 2020). "A higher DCR of tumor and AFP response and a significantly longer median TTP and median OS were observed in the TACE–apatinib group before and after the PSM analysis." (PMID 32733791, 2020). "In this study, AFP was the tumor antigen and was required for AFP-derived epitope-specific T cell activation." (PMID 32132566, 2020). "Regression coefficients of the factors were 0.832 (ALBI grade), 0.533 (maximal tumor diameter), 0.460 (AFP), and 0.650 (initial TACE response)." (PMID 32487089, 2020). "The risk of HCC recurrence varies between 8 and 20% depending on pre-transplant-variables such as the tumor burden and the alpha-fetoprotein (AFP) level." (PMID 32351877, 2020).
tumor (continued). "The tumor markers alpha-fetoprotein (AFP), carcinoembryonic antigen (CEA), and carbohydrate antigen 19-9 (CA19-9) were elevated in 72, 32, and 51 patients, respectively." (PMID 32382558, 2020). "Like AFP, β-hCG can be produced by other tumors and thus influence diagnostics and should be considered when decision making is based on this tumor marker." (PMID 32235691, 2020). "The tumor markers carcinoembryonic antigen, alpha fetoprotein, and carbohydrate antigen 199 stayed in normal ranges; carbohydrate antigen 125 was 19.76U/mL (normal for 0–5U/mL)." (PMID 33327238, 2020). "Our nomogram also included four common factors: age, serum AFP, tumor size, and satellite nodules; for these, we included demographic characteristics, serum indicators, and clinicopathological data to optimize the overall predictive ability." (PMID 33163397, 2020). "The ROC curves of AFP, tumor diameter, preoperative CTC count and multiparameter combination were drawn, and the areas under the ROC curves (AUCs) of these variables were 0.636, 0.604, 0.856, and 0.900, respectively." (PMID 33129301, 2020). "Tumor responses at 3 months and AFP responses at 4 weeks after the first TACE treatment between the two groups before and after PSM analysis." (PMID 32733791, 2020). "HCC patients in the FOXC2-Hi group showed more aggressive clinicopathologic characteristics, including higher serum AFP levels, larger tumor size, more recurrence, lower tumor differentiation, and later clinical stage." (PMID 32508532, 2020). "On ROC analysis, tumor size cutoff of 3 cm (Area under curve = 0.64, P = 0.04) and AFP cutoff of 600 ng/mL (Area under curve = 0.66, P–value = 0.03) were significant variables for recurrence." (PMID 33553240, 2020). "The comparison between low and high AFP of tumor samples showed that 3.5% of intact glycopeptides changed at glycosylation occupancies." (PMID 32426269, 2020). "Primary tumor markers such as Alpha-fetoprotein (AFP) and Beta human chorionic gonadotropin (ß-hCG) were normal." (PMID 33032570, 2020). "In the univariate analysis, there was a significant difference between both groups in serum AFP level (P = 0.02), tumor diameter (P = 0.01), Milan criteria (P = 0.001), operative blood loss (P = 0.03), operative time (P = 0.04), hospital stay (P = 0.04)." (PMID 32368340, 2020). "Some tumor specific glycan subtypes were commonly increased in both low and high AFP tumors compared with their paracancers, which were mainly high-mannose (54/126, 42.8%) and bi-antennary glycans with 1-2 sialic acids (35/126, 27.8%)." (PMID 32426269, 2020). "Up to now, several chemiluminescent immunoassay methods have been established in the clinical detection of tumor markers, such as alpha-fetoprotein (AFP), prostate-specific antigen (PSA), carbohydrate antigen 125 (CA125), and neuron-specific enolase (NSH)." (PMID 32552818, 2020). "To accomplish this, we first performed serials of in vitro assays to select TCRs with potent activity against AFP-expressing tumor cells." (PMID 32425926, 2020). "We found that CD13high patients displayed the clinical manifestations of elevated alpha‐fetoprotein (AFP), tumor encapsulation, and vascular invasion (All P value < .05)." (PMID 33377659, 2020). "It is difficult to differentiate HYST from HCO as the size of the tumor and serum level of AFP rapidly increases with tumor progression in both cases." (PMID 32384467, 2020). "Given the overlap of four prognostic parameters (albumin, bilirubin, AFP and tumour size) which are dichotomized in the HAP and SAP scores, this is not unexpected." (PMID 31579990, 2020).